Y_RNA (Y RNA )
Gene: Miscellaneous RNA gene on chromosome 1 (8,796,571 to 8,796,673, reverse strand). Ensembl gene ENSG00000222511.
Homologues: Orthologues: chimpanzee Y_RNA (100% identical), macaque Y_RNA (89% identical). Paralogues in human: Y_RNA (79% identical), Y_RNA (78% identical), Y_RNA (77% identical), Y_RNA (76% identical), RNY1P5 (75% identical), Y_RNA (75% identical), Y_RNA (74% identical), RNY1P1 (73% identical), Y_RNA (73% identical), RNY1P6 (72% identical), Y_RNA (72% identical), Y_RNA (71% identical), and 90 more.